IL1A (interleukin 1 alpha)
Diseases named in the same sentence as IL1A in open-access papers (continued):
Sharing a sentence is not in itself a finding about the gene and the disease.
dry eye (12 papers, 2009 to 2023). "Similar to the effects seen with DOPG, topical doxycycline in mouse models of dry eye reduces expression of IL-1α, IL-1β, and TNF-α, and in LPS-stimulated corneal epithelial cells, it has been shown to reduce IL-1β transcription and translation." (PMID 36982926, 2023). "Clinical studies reported that tears of dry-eye patients had increased levels of interleukin-1 alpha (IL-1α) and interleukin-1 beta (IL-1β), which were associated with corneal fluorescein staining." (PMID 34876936, 2021). "Both inflammatory expression products (IL-1α, and IL-17A with p = 0.030 and p = 0.004) were upregulated in untreated dry eye, compared to control." (PMID 33057006, 2020). "A vehicle-effect was also observed, indicating that ocular wetting does lower IL-1α levels compared to untreated dry eye in this animal model." (PMID 33057006, 2020). "A study in patients with thyroid orbitopathy (TO) related dry eye, demonstrated increased levels of conjunctival cytokines IL-1α, IL-1β and IL-6 in IC samples using immunofluorescence." (PMID 30673862, 2019). "Clinical studies have reported that tears of dry eye patients show increased levels of IL-1α and mature IL-1β which correlated to corneal fluorescein staining." (PMID 30673862, 2019). "Dry eye patients were found with higher levels of proinflammatory cytokines such as IL1α along with IL-1β, IL-6, IL-8, and tumor necrosis factor (TNF-α) in the tear film compared to normal controls." (PMID 30519584, 2018). "Proinflammatory cytokines interleukin-1α (IL-1α), and interleukin-1β (IL-1β) have been detected in human conjunctival epithelium and tear film in dry eye." (PMID 19190733, 2009). "IL-1α, IL-6, IL-12, IFN-γ, and RANTES have been documented to be increased in the tears of dry eye patients." (PMID 28379171, 2017). "Studies by Pflugfelder and others have shown that the concentrations of inflammatory cytokines such as IL-1a, IL-6, IL-8 and TNF-α are increased in the conjunctival epithelium of patients with Sjögren syndrome, which is characterized by severe dry eye symptoms." (PMID 30096194, 2018). "IL-1α, TNF-α and Il-10 were not modified by dry-eye condition in comparison with the basal level." (PMID 34959420, 2021).
fungal infection (12 papers, 2015 to 2025). "A clear link between CLRs and IL-1α/β signaling exists, as evidenced by CARD9-deficient patient’s reduced IL-1α/β expression and susceptibility to fungal infection." (PMID 33643264, 2021). "In this study, we addressed the mechanisms underlying IL-1α secretion and its functional role on the host resistance to fungal infection." (PMID 31425553, 2019). "Neutrophil recruitment linked to IL-1α upregulation have been shown to contribute to the development of lethal lung pathology during fungal infection with Aspergillus." (PMID 28919893, 2017). "Immediately after systemic infection with C. albicans, the expression of IL-1α, IL-1β, and IL-1R is rapidly upregulated in the kidneys, possibly suggesting a role in the host defense against fungal infection." (PMID 40097388, 2025). "IL-1α is a potent pro-inflammatory cytokine that not only activates TNFα signaling but also recruits neutrophils to the site of fungal infection." (PMID 41081505, 2025). "M-CSF, IL-1α and IL-19 concentration in the hemolymph after fungal infection, and significantly lower TNF-β and G-CSF." (PMID 38774871, 2024). "Following their induction during fungal infection, both IL-1α/β play a key role orchestrating the immune response." (PMID 33643264, 2021). "While the broad and potent consequences of IL-1α/β and IL-33 signaling are known, the induction of these cytokines during fungal infection is less clear." (PMID 33643264, 2021). "To better characterize the biological role of IL-1α, we first analyzed the kinetics of IL-1α production over the time of fungal infection." (PMID 31425553, 2019). "In this study, we investigated the steps necessary for IL-1α-mediated inflammation and its implications after fungal infection." (PMID 31425553, 2019). "Interestingly, a fungal infection of Il1a-/- BMDMs resulted in reduced IL-6 production, whereas exogenous rIL-1α rescued IL-6 levels." (PMID 31425553, 2019). "Lichochalcone-A was found to significantly decrease the expression of pro-inflammatory cytokines IL-1α and IL-1β, suggesting it may have a modulatory role on the host pro-inflammatory response to help eradicate fungal infections." (PMID 27284694, 2016).
gout (12 papers, 2009 to 2025). A condition characterized by painful swelling of the joints, which is caused by deposition of urate crystals. "Then, it was found that the IL1A (interleukin 1 alpha) was the only one gene related to Toll-like receptor signaling pathway that was associated with the occurrence of gout." (PMID 38164346, 2024). "In conclusion, through bioinformatic analysis on GSE199950 dataset, we find that IL1A is a risk factor for gout patients, and it has a good clinical diagnostic value." (PMID 38164346, 2024). "Then, according to the ROC curve, we calculated the AUC value of IL1A to be 1.000 and the CI to be 1.000-1.000, indicating a good diagnostic ability for the gout patients." (PMID 38164346, 2024). "In addition, the ROC curve also showed that IL1A has significant clinical diagnostic value for clinical gout patients." (PMID 38164346, 2024). "By demonstrating that IL1A knockdown attenuates pro-inflammatory signaling and protects endothelial cells in a co-culture model, we provide new insights into how IL-1α may sustain gout-associated inflammation through intercellular communication." (PMID 40657393, 2025). "Moreover, IL1A is highly expressed in gout patients,it has a good clinical diagnostic value." (PMID 38164346, 2024). "IL-1α may be implicated in the local induction and amplification of gouty arthritis." (PMID 33926105, 2021). "Although IL-1β has been extensively studied in the pathophysiology of gout, the role of IL-1α remains relatively underexplored." (PMID 40657393, 2025). "In vivo validation in gout animal models or clinical patient samples will be essential to confirm the translational potential of targeting IL-1α." (PMID 40657393, 2025). "The role of IL1A in promoting inflammatory responses is vital as it directly contributes to the progression of gout." (PMID 40657393, 2025). "And in PBMCs, the expression level of IL1A in gout patients was higher than that in normal healthy group." (PMID 38164346, 2024). "Through the bioinformatics analysis on samples in this dataset, hub gene (IL1A) and key pathway (Toll like receptor signaling pathway) related to gout were identified." (PMID 38164346, 2024). "Alternatively, IL-1α, IL-1β, and IL-18 drive pathology in a range of human diseases, such as gouty arthritis, autoinflammatory disease, or cytokine storm in systematic infectious diseases." (PMID 36551320, 2022). "It is possible that IL-1β and IL-1α are released from dead cells with the gout-inflicted joint leading to the induction of caspase-11 in an IL-1R-dependent manner, priming immune cells for inflammasome activation by subsequent insults including MSU." (PMID 31803174, 2019). "Future studies could explore IL-1α neutralization in animal models of gout to evaluate the therapeutic potential suggested by our in vitro findings." (PMID 40657393, 2025). "In PBMCs, IL1A levels in gout patients were higher compared to HCs." (PMID 38164346, 2024). "Therefore, we conclude that IL1A promotes the development of gout by up-regulating Toll-like receptor signaling pathway." (PMID 38164346, 2024). "Anakinra, an IL-1 receptor antagonist that inhibits the activity of both IL-1α and IL-1β, is effective in reducing acute gout pain and inflammation and may be a reasonable option in patients with CKD." (PMID 37014501, 2023). "Given the efficacy of IL-1 receptor antagonists in gout, neutralizing antibodies against IL-1α may also be beneficial." (PMID 35464445, 2022). "IL-1α can be found asa cell-bound molecule on the plasma membrane in epithelial cells and can be considered as tissue damage and then, begins triggering the early phases of gout flare with severe pains." (PMID 30871515, 2019). "Therefore, we conclude that IL1A may participate in the inflammation of gout through positively regulating Toll like receptor signaling pathway." (PMID 38164346, 2024). "Therefore, we conclude that IL1A may participate in the inflammatory response of gout through Toll-like receptor pathway." (PMID 38164346, 2024).
gout (continued). "Targeting IL1A, either alone or in combination with TLR4 suppression, may be a promising treatment strategy for gout-related inflammation and tissue damage." (PMID 40657393, 2025). "Conversely, IL-1α, IL-6, IL-12(p40), G-CSF, MCP-1, and TNF-α, which could be induced by gouty arthritis, were significantly reduced by Simiao decoction and febuxostat." (PMID 32670069, 2020). "This study also did not directly assess the relative contributions to chronic gouty arthritis of IL1α and IL1β, both of which are inhibited by rilonacept." (PMID 19635719, 2009).
Cerebral ischemia (11 papers, 2011 to 2025). Restriction of arterial blood supply to the brain associated with insufficient oxygenation to support the metabolic requirements of the tissue. "Studies have shown that neuroinflammation and cerebral ischemia are mediated by the secretion of IL‐1α, TNF‐α, and complement 1q (C1q) by classically activated microglia (M1 type)." (PMID 41395456, 2025). "Expression of IL-1α protein is also seen after cerebral ischemia, as early as 4 h post-reperfusion in microglial cells." (PMID 25705177, 2015). "IL-1β and IL-1α levels were undetectable in IL-1α/β KO mice and IL-1α displayed a significant increase after cerebral ischemia in the ipsilateral hemisphere (two-way ANOVA followed by Bonferroni’s post hoc test, P < −0.05, not shown)." (PMID 23024646, 2012). "In order to determine this we investigated the temporal and spatial profiles of IL-1α and IL-1β expression after cerebral ischemia." (PMID 22206506, 2011). "After cerebral ischemia, IL-1a express in microglia, astrocytes, and endothelial cells, inducing activation of astrocytes and endothelial cells and promoting formation of tube-like structure that is an important hallmark of angiogenesis, knockout IL-1a in mice can reduce ischemic damage." (PMID 37292135, 2023). "Finally, a recent study reported neuroprotective effects of sub-pathological systemic IL-1α doses before brain ischemia." (PMID 33770265, 2021). "Similarly, levels of IL-1α—released in the ischemic brain by injured cells and platelets—raise after 7 days in murine models of cerebral ischemia/reperfusion injury and facilitate neutrophil infiltration and BBB damage." (PMID 33770265, 2021). "Astrocytes during cerebral ischemia mainly activate NF‐κB, signal transducers, and the STAT3 pathway to induce inflammatory cytokines (IL‐6, IL‐1α, IL‐1β, TNF‐α, and interferon‐γ, among others) and release neurotoxic mediators (including NO and ROS), leading to neuronal damage and death." (PMID 41395456, 2025). "Cerebral ischemia activates innate immune receptors on microglia/macrophages and other cells resulting in the release of cytokines and chemokines such as IFN-γ, TNF-α, and IL-1α." (PMID 33514001, 2021). "Similarly IL-1α production and nuclear localization are correlated to ROS levels, EGFR activation and MEK/ERK in fibrosarcoma, skin keratinocytes and in cerebral ischemia injury." (PMID 26919242, 2016). "IL-1β mRNA is detected within 3-6 h after cerebral ischemia, although there is very little direct evidence that IL-1β protein is produced, and almost no information is available about IL-1α." (PMID 22206506, 2011). "Over-expression of IL-1α/β in alveolar macrophages during ARDS and over-production of IL-1α (but no IL-β) in platelets during heart and brain ischemia stimulates the migration of inflammatory cells through inducing the expression of chemokines and adhesion molecules on endothelial cells." (PMID 35126355, 2021).
Cognitive impairment (11 papers, 2018 to 2025). Abnormal cognition is characterized by deficits in thinking, reasoning, or remembering. "For example, our data suggest that IL-1α/β and C1q are elevated during acute infection, and they have both been implicated in virally-mediated cognitive deficits previously." (PMID 39610883, 2025). "Consistent with links between senescence and cognitive impairment, we found inverse correlations between time spent exploring Y maze's open arm and the frequency of p21, Il1α and Il6 positive cells in the hippocampus." (PMID 39374134, 2025). "Elevated IL-1α is further observed in the cerebrospinal fluid of PLWH and is positively associated with a risk of cognitive impairment." (PMID 38786105, 2024). "Here, we show for the first time that therapeutically targeting IL-1RI may be more likely to provide effective treatment for patients suffering cognitive deficits after TBI than drugs that specifically target individual IL-1α and IL-1β signaling." (PMID 29662944, 2018).
fibrosarcoma (11 papers, 2013 to 2024). A malignant mesenchymal fibroblastic neoplasm affecting the soft tissue and bone. "3-MCA-induced fibrosarcoma cell lines, from IL-1a-deficient mice, showed that host-derived IL-1α is involved in cancer immunoediting by affecting innate and adaptive immunosurveillance mechanisms." (PMID 32825489, 2020). "It was hypothesized that the membrane-associated IL-1α on the fibrosarcomas may be able to interact with immune effector cells bearing IL-1R, thus activating them and inducing the anti-tumor activities." (PMID 33430381, 2021). "However, membrane-associated IL-1α expression in fibrosarcoma cells was shown to reduce tumorigenicity by inducing antitumor immunity in wildtype mice." (PMID 24901233, 2014). "Nevertheless, PLGA IL‐1α‐MP administration (equivalent to 0.2 μg/mouse) to NFS/N mice bearing malignant fibrosarcoma tumors showed significantly longer survival rates compared to experimental controls although no toxicity end points were analyzed in vivo." (PMID 37206237, 2023). "The authors found that at the injection sites of IL-1α positive fibrosarcoma cells, CD 8+ T-cells, NK-cells and macrophages accumulated there." (PMID 33430381, 2021). "Overexpression of IL1α in fibrosarcoma lines appears to induce antitumor immunity mediated by innate immune cells." (PMID 33931964, 2021). "In a 3-MCA-induced fibrosarcoma cell line, IL-1α expression was required for tumor development when implanted into mice." (PMID 33430381, 2021). "Overall, cytosolic or membrane-bound IL-1α in fibrosarcoma seems to induce anti-tumor activity via activation of immune cells." (PMID 33430381, 2021). "Conversely, when studying the cytosolic full length and membrane form of IL-1α on fibrosarcoma, many other studies show a suppressive effect on tumor growth." (PMID 33430381, 2021). "IL-1α expression was also essential for tumor development following implantation of the 3-MCA-induced fibrosarcoma cell line, with findings from this study highlighting an important role for IL-1α in controlling immune-surveillance of the developing tumor." (PMID 31231372, 2019). "On the other hand, fibrosarcoma cells expressing IL-1α in the cytosol and on the cell membrane lost their tumorigenesis, suggesting cell-associated IL-1α could stimulate anti-tumor immune responses." (PMID 28152513, 2017). "These CTLs were important for tumor eradication, and the authors also found that fibrosarcomas that do not produce cytosolic or membrane-bound IL-1α can be induced to do so via treatment with cytokines or LPS." (PMID 33430381, 2021). "Thus, we have shown that transplantable 3-MCA-induced fibrosarcoma cell lines obtained from IL-1α−/− mice failed to induce tumors in immune intact mice, whereas in sublethally irradiated mice, tumors do develop." (PMID 23847618, 2013). "Regression of tumors from IL-1α-positive fibrosarcoma cells does not require activation of CD4+ T cells, which suggests that cell-associated IL-1α may act as a membrane-associated co-stimulatory molecule or focused adjuvant that directly activates CD8+ T cells." (PMID 23847618, 2013).
ischemia (11 papers, 2011 to 2023). A hypoperfusion of the BLOOD through an organ or tissue caused by a PATHOLOGIC CONSTRICTION or obstruction of its BLOOD VESSELS, or an absence of BLOOD CIRCULATION. "When recombinant IL-1β was injected into the lateral ventricles or directly into the brain parenchyma in the animal models, the levels of IL-1α and IL-1β significantly increased, which would result in ischemia or other causes of brain damage." (PMID 24063019, 2013). "Antagonism of IL-1 receptors has been shown to alter lymphocyte and macrophage infiltration, and IL-1α/β knock out mice exhibit reduced acute tubular necrosis between 24 and 48 h after ischemia." (PMID 37362447, 2023). "For inflammatory cytokines, on day 14, intramuscular transplantation of hiPSC-MSCs in the MSC-Saline, MSC-MSC/once, MSC-MSC/week and MSC-MSC/3 days groups significantly decreased IL-1A and IL-17A compared with the ischemia group (all p < 0.05)." (PMID 36008710, 2022). "Several stimuli including glutamate, IL-1α, hypoxia, TNFα, and reactive oxygen species seen in ischemia can activate NF-κB." (PMID 33953854, 2021). "As a proof of concept, we investigated whether MLR-HFS starting in the acute phase of ischemia and continued for 24 h was associated with an attenuation of proinflammatory mediators, namely IFN-γ, TNF-α, and IL-1α in the cerebral tissue surrounding the photothrombotic lesion." (PMID 33514001, 2021). "mRNA levels of proinflammatory cytokines, IL-1α, IL-6, and TNF-α, were significantly higher in the I/R group 2 h after the reperfusion period following ischemia compared with the control group (IL-1α, p < 0.05; IL-6, p < 0.0001; TNF-α, p < 0.01)." (PMID 33843175, 2021). "We used IL-1α and β KO mice because it has been reported that IL-1α -or β-alone KO mice do not give rise to the neuroprotective phenotype after ischemia." (PMID 22483094, 2012).